SSTR5 (somatostatin receptor 5)
Diseases named in the same sentence as SSTR5 in open-access papers (continued):
Sharing a sentence is not in itself a finding about the gene and the disease.
paraganglioma (3 papers, 2017 to 2025). A benign or malignant neoplasm arising from paraganglia located along the sympathetic or parasympathetic nerves. "We first scanned relative expression level of SSTR5 in various tumor types in GEPIA dataset and found significant downregulation of SSTR5 in most of the tumor types including adrenocortical carcinoma (ACC), kidney renal clear cell carcinoma (KIRC), and pheochromocytoma and paraganglioma (PCPG)." (PMID 31196171, 2019).
small cell lung carcinoma (3 papers, 2017 to 2024). Small cell lung cancer (SCLC) is a highly aggressive malignant neoplasm, accounting for 10-15% of lung cancer cases, characterized byrapid growth, and early metastasis. "The small cell lung cancer cell line NCI-H69 was devoid of SSTR1 expression but strongly expressed SSTR2, SSTR3, and SSTR5." (PMID 29282035, 2017).
thyroid cancer (3 papers, 2014 to 2022). "While several studies have demonstrated SSTR2 positivity in thyroid cancers, other studies have demonstrated a relative abundance of other SSTR subtypes, such as SSTR5, in these tumors." (PMID 35712243, 2022).
laryngeal squamous cell carcinoma (2 papers, 2021 to 2024). A squamous cell carcinoma that arises from the larynx. "SSTR5 expression is restrained in laryngeal squamous cell carcinoma to play an anti‐tumor effect, and its expression is modulated by DNA methylation and histone modification." (PMID 38721812, 2024). "SSTR5 expression in primary human laryngeal squamous cell carcinoma tissue demonstrated to be significantly lower compared to corresponding normal tissue." (PMID 33085037, 2021).
liver cancer (2 papers, 2013 to 2025). An epithelial or non-epithelial malignant neoplasm that arises from the liver. "The absence of SSTR2 and SSTR5 may explain the lack of local response to octreotide therapy in certain advanced liver cancers." (PMID 24137418, 2013).
prolactinomas (2 papers, 2022 to 2025). "It has been proposed as an alternative treatment method in DA-resistant prolactinomas, especially in those with high SSTR5 expression, and several cases with optimal outcomes have been reported in recent years." (PMID 35683457, 2022). "Somatostatin receptor (SSTR) expression in prolactinomas is very variable with a predominance of SSTR5, followed by SSTR2A and SSTR1." (PMID 35683457, 2022).
type 2 diabetes (2 papers, 2018 to 2023). "The findings of this study provide deeper insights into the mechanism by which SSTR5 inhibition affects type 2 diabetes and will help to facilitate the development of effective therapeutic strategies against insulin resistance in type 2 diabetes." (PMID 36585794, 2023). "Collectively, our results demonstrate that selective SSTR5 inhibition can improve insulin sensitivity by enhancing liver insulin action; thus, selective SSTR5 antagonists represent potentially novel therapeutic agents for type 2 diabetes." (PMID 36585794, 2023). "Our results also suggest that the liver is one of the target organs of this mechanism; therefore, selective SSTR5 antagonists may represent a novel and attractive therapeutic agent for type 2 diabetes." (PMID 36585794, 2023).
acute lymphoblastic leukemia (1 paper, 2020). Leukemia with an acute onset, characterized by the presence of lymphoblasts in the bone marrow and the peripheral blood. "SSTR-3 and SSTR-5 were detected only in malignant specimens, such as rhabdomyosarcoma, Hodgkin lymphoma, acute lymphoblastic leukemia, and a single nonmalignant condition, hereditary spherocytosis." (PMID 33297556, 2020).
benign prostatic hyperplasia (1 paper, 2022). A non-cancerous nodular enlargement of the prostate gland. "Consistently, endogenous CORT was overexpressed in PCa samples (compared with benign-prostatic-hyperplasia) and correlated with key clinical (i.e., metastasis) and molecular (i.e., SSTR2/SSTR5 expression) parameters." (PMID 36361790, 2022).
brain infarct (1 paper, 2021). "Accordingly, SST and a related peptide, cortistatin-14, and the synthetic SSTR2, SSTR3, and SSTR5 agonist octreotide significantly reduce brain infarct size in a middle cerebral artery occlusion model." (PMID 34803662, 2021).
dilated cardiomyopathy (1 paper, 2024). Cardiomyopathy which is characterized by dilation and contractile dysfunction of the left and right ventricles. "SSTR5 would be considered expressed in control and dilated cardiomyopathy samples by both the more and less restrictive thresholds." (PMID 39038008, 2024).
endometriosis (1 paper, 2025). The growth of functional endometrial tissue in anatomic sites outside the uterine body. "These correlation analyses underscore the significant involvement of the key anti-endometriosis targets (SSTR5, CASP3, FABP2, and SYK) in modulating immune cell infiltration and immune-related pathways." (PMID 39754173, 2025). "Machine learning identified SSTR5, CASP3, FABP2, and SYK as critical targets, contributing to a nomogram that demonstrated good predictive performance for endometriosis risk." (PMID 39754173, 2025). "The correlation between gene expression of the four key anti-endometriosis targets (SSTR5, CASP3, FABP2, and SYK) and immune cell infiltration was analyzed." (PMID 39754173, 2025). "The expression profiles of the four key anti-endometriosis targets (SSTR5, CASP3, FABP2, and SYK) were analyzed." (PMID 39754173, 2025). "Four common key targets (SSTR5, CASP3, FABP2, and SYK) were identified across all three machine learning methods, suggesting their crucial role as therapeutic targets for the anti-endometriosis effects of monoterpene glycosides from Paeonia lactiflora." (PMID 39754173, 2025). "SSTR5, KCNH2, CASP3, PTGER1, PPARD, and TYMP emerged as the top-ranked targets, indicating their potential significance in the treatment of endometriosis." (PMID 39754173, 2025).
fibrous tumors (1 paper, 2021). "The differences were less prominent for SSTR5, but SSTR5 expression was higher in meningothelial tumors than in both fibrous (p = 0.019) and transitional tumors (p = 0.038), and higher in atypical tumors, compared to fibrous tumors (p = 0.037)." (PMID 34830858, 2021).
Graves ophthalmopathy (1 paper, 2019). An autoimmune disorder of the EYE, occurring in patients with Graves disease. "Somatostatin receptors, especially SSTR-2 and SSTR-5 subtypes, with high affinity for octreotide are found in retro-ocular muscles and retrobulbar fat of Graves’ ophthalmopathy." (PMID 31463594, 2019).
Hashimoto thyroiditis (1 paper, 2020). An autoimmune disorder caused by the production of autoantibodies against thyroid tissue. "68Ga-DOTATOC, a somatostatin analog that predominantly targets SSTR-2 and SSTR-5 has demonstrated increased uptake in five of eight cases of Hashimoto’s thyroiditis." (PMID 33551992, 2020).
hyperprolactinemia (1 paper, 2021). Abnormally high level of prolactin in the blood. "Since SSTR5 is more important in PRL release regulation, somatostatin analogues with improved selective binding affinity for SSTR5 subtype may be effective in the treatment of hyperprolactinemia." (PMID 34681905, 2021).
Hypoglycemia (1 paper, 2021). A decreased concentration of glucose in the blood. "If SSTR-2, SSTR-3 and SSTR-5 are not expressed or have a low tumor expression, SSAs can lead to paradoxical hypoglycemia because they also inhibit counterregulatory hormone secretion (i.e., glucagon and growth hormone)." (PMID 34199977, 2021).
Insulin resistance (1 paper, 2023). Increased resistance towards insulin, that is, diminished effectiveness of insulin in reducing blood glucose levels. "High‐fat diet (HFD)‐fed SSTR5 KO mice exhibited significantly lower homeostasis model assessment of insulin resistance (HOMA‐IR) than HFD‐fed wild‐type mice." (PMID 36585794, 2023). "In this study, we investigate the effects of SSTR5 inhibition on insulin resistance in vivo." (PMID 36585794, 2023). "Therefore, in this study, we investigate the effect of SSTR5 blockade on insulin resistance and the target organ using SSTR5 KO mice and a selective SSTR5 antagonist (compound‐1)." (PMID 36585794, 2023). "Finally, we investigate the target organ by which selective SSTR5 antagonists alleviate insulin resistance using a hyperinsulinemic‐euglycemic clamp technique in male KK‐Ay mice and measuring insulin‐induced Akt phosphorylation in male C57BL/6J mice." (PMID 36585794, 2023). "To evaluate the effects of SSTR5 deletion on insulin resistance induced by HFD feeding for 4 weeks, we measured HOMA‐IR, an index of insulin resistance." (PMID 36585794, 2023). "To determine whether these hormones participate in the insulin‐sensitizing action of SSTR5 inhibition, we evaluated the effects of alogliptin, a dipeptidyl peptidase 4 (DPP4) inhibitor that increases plasma GLP‐1 and insulin levels, on insulin resistance in KK‐Ay mice." (PMID 36585794, 2023).
laryngeal carcinoma (1 paper, 2016). Carcinoma that arises from the laryngeal epithelium. "Previous laryngeal cancer study has shown that the overall pattern of SSTRs expression is with high levels of SSTR1, “loss” of SSTR2 and intermediate levels of SSTR5." (PMID 26796520, 2016).
lymphoma (1 paper, 2024). A malignant (clonal) proliferation of B- lymphocytes or T- lymphocytes which involves the lymph nodes, bone marrow and/or extranodal sites. "SSTR5 was found to be expressed more than all other SSTRs in MALT-type lymphomas, and to be more expressed in gastric-type lymphomas, along with SSTR3 and SSTR4, compared to extragastric ones; in addition, the presence of SSTR5 in lymphomas was found to correlate with a more favorable prognosis." (PMID 39329930, 2024).
neurofibroma (1 paper, 2021). An intraneural or extraneural neoplasm arising from nerve tissues and neural sheaths. "SSTR1 and SSTR5 presented the same immunoreactivity, as one case of neurofibroma and one case of schwannoma were negative and the other tumor samples were positive." (PMID 34830858, 2021).
Obesity (1 paper, 2023). Accumulation of substantial excess body fat. "HFD‐fed SSTR5 KO mice exhibited lower HOMA‐IR than HFD‐fed WT mice at similar BW levels, indicating that SSTR5 deletion maintains insulin sensitivity even under HFD‐induced obesity." (PMID 36585794, 2023). "Although a HFD induced obesity and abnormal glucose metabolism, HFD‐fed SSTR5 KO mice showed significantly decreased PG, plasma insulin, and GHb levels compared with HFD‐fed WT mice." (PMID 36585794, 2023).
Sepsis (1 paper, 2020). Sepsis is defined as life-threatening organ dysfunction caused by a dysregulated host response to infection. "The specific SST receptor SSTR5 in the intestinal barrier was detected increased by SST in mice with sepsis in this research, so we inferred that SST/SSTRs probably activated the anti-inflammation pathway in septic mouse." (PMID 33376482, 2020).
somatotropic adenomas (1 paper, 2022). "The occurrence of SSTR2a and SSTR5 in all or at least the majority of somatotropic adenomas was reported in earlier studies." (PMID 34674191, 2022). "SSTR2 und SSTR5 are the most prominent in somatotropic adenomas according to the current literature." (PMID 34674191, 2022). "In this study, we investigated expression of SSTR2a and SSTR5 in surgically resected somatotropic adenomas of the pituitary gland." (PMID 34674191, 2022).
thyroid tumor (1 paper, 2022). A benign or malignant neoplasm affecting the thyroid gland. "These “fourth-generation analogs” have been reported to show very high affinity for SSTR2, SSTR3, and SSTR5 and intermediate-high affinity for SSTR4, which possibly make them good candidates for thyroid tumor cells that express high levels of SSTR3 or 5, despite low expression of SSTR2." (PMID 35453992, 2022).
tumor (100 papers, 1997 to 2025). "Liver metastases from ileal NENs have also been found to show a higher expression of SSTR5, which is potentially linked to tumour aggressiveness." (PMID 36980746, 2023). "The loss of somatostatin receptor 5 was observed between the second and third tumor resection." (PMID 35602875, 2022). "The aim of the present study was to evaluate the impact of USP8 mutations on SSTR5 expression and their correlation with responsiveness to pasireotide in primary cultures from surgically removed human corticotrophs tumors and murine corticotroph tumor cells AtT-20." (PMID 35626057, 2022). "As mentioned in the previous sections, Merkel carcinoma cells preferentially express SSTR2 and SSTR5, meaning that in theory octreotide must be effective in such neoplasias." (PMID 39329930, 2024). "Finally, this important effect on headache may be related to the tumor expression of a truncated somatostatin receptor 5 variant, as described in two cases of patients with severe headaches and no biochemical effects of octreotide, but a good response to Pas-LAR." (PMID 38362280, 2024). "For lung NECs, the predominant SSTRs are SSTR2A and SSTR1, with SSTR4 and SSTR5 less frequently expressed, depending on the degree of differentiation of the tumor." (PMID 39329930, 2024). "Quantification of the SSTR3, SSTR2, and SSTR5 transcript levels in tumor tissues revealed a similar expression of SSTR3 compared to SSTR2 and SSTR5 in our cohort of patients." (PMID 38612419, 2024). "Pasireotide long-acting release, which acts on the somatostatin receptor subtype 5 (SSTR5), is used when the tumor is resistant to first-generation drugs." (PMID 36826759, 2023). "SSTR2 immunostaining was strong and diffuse in seven of the eight tumours, and SSTR5 was present in seven tumours although intensity of staining was weak." (PMID 37851558, 2023). "Out of which, the SSTR2 and SSTR5 have gained significant attention due to their role in mediating the inhibition of growth hormone and antiproliferative effects of somatostatin on tumor growth." (PMID 37770425, 2023). "SSTR5 was found to be highly expressed in control and tumor tissue often with high and frequent expression in colorectal cancer in association with decreased expression with tumor stage." (PMID 38203605, 2023). "SSTR5 expression was also investigated in murine corticotroph tumor AtT-20 cells, endogenously expressing USP8 wild-type." (PMID 35626057, 2022). "Immunostaining for SSTR5 in liver metastatic lesions was performed in 1 patient, and the tumor was positively stained." (PMID 35265125, 2022). "SSTR5 upregulation was observed in USP8 wild-type primary tumor cells transfected with S718del USP8 mutant." (PMID 35626057, 2022). "Among benign conditions, SSTR5 has been noted to be prevalent in ectopic and eutopic endometrial tissue, which is often difficult to differentiate from neoplasms." (PMID 35890290, 2022). "Six different somatostatin receptor types (SSTR1, SSTR2A, SSTR2B, SSTR3, SSTR4, and SSTR5) have been detected in numerous different human tissues as well as several tumor types." (PMID 33899156, 2022). "Gene expression levels of SSTR2 and SSTR5 within hPITO28 and 34 correlated with protein levels within the patient’s tumor tissue." (PMID 36359740, 2022). "The expression of SSTR2 and SSTR5 varied significantly between tumor subtypes (p < 0.001 and p = 0.003, respectively)." (PMID 34830858, 2021). "As a somatostatin receptor, SSTR5 plays a variety of biological roles on normal and tumor tissue targets by interacting with somatostatin." (PMID 33169793, 2020). "Tumours with low E‐cadherin score expressed higher levels of SSTR5 while tumours with high E‐cadherin score displayed lower SSTR5 protein levels." (PMID 30843342, 2019). "Since commonly used substances have a high affinity to SSTR2A and SSTR5, one would expect recurrent tumor tissue to have lower expression rates." (PMID 30627156, 2018).
tumor (continued). "In this study, the expression of mRNA for SSTR-2 was studied in 46 UM specimens, and SSTR-5 in 9 UM tumor samples." (PMID 29949880, 2018). "Between the SSTR5 or CXCR4 positivity of tumor microvessels and all other pathological or clinical parameters recorded no further significant association was found." (PMID 29282035, 2017). "SSTR5 expression on tumor microvessels was observed in 34% of the HCC samples and in 44% of the CCC samples." (PMID 29282035, 2017). "Independent from the tumor cells, many samples displayed strong staining for SSTR5 and CXCR4 on capillaries of the tumor stroma." (PMID 29282035, 2017). "In their research, it was observed that the silencing of FLNA in both human primary cultures of corticotrophinomas and in murine tumor cells resulted in a significant downregulation of SSTR5 expression, as well as the abolition of Pasireotide-induced antiproliferative and pro-apoptotic effects." (PMID 40364036, 2025). "SSTR3, SSTR2, and SSTR5 expression in tumor tissues was analyzed by qRT-PCR and Western blot." (PMID 38612419, 2024). "In addition, the presence of somatostatin receptors (mainly SSTR5) and epidermal growth factor receptors (EGFR) have been linked to tumor aggressiveness and resistance to dopamine agonists (DA)." (PMID 37529607, 2023). "The tumours causing GH excess expressed both SSTR2 and SSTR5." (PMID 37851558, 2023). "In vitro studies, strong SSTR-5 expression was shown in corticotropic tumor cells in CD." (PMID 36161631, 2022). "Two of the most effective treatments for patients with NET (i.e., SSAs and peptide radionuclide therapy) depend on the expression of SSTR2 and SSTR5 on the tumor cell surface, and these SSTRs are crucial therapeutic targets for SSAs and peptide radioreceptor therapy in NET treatment." (PMID 36555512, 2022). "SSTR-5 expression in corticotropic tumor cells and high affinity of pasireotide may explain the potential effect of pasireotide on CD." (PMID 36161631, 2022). "However, SSTR5 can suppress tumor cell proliferation by influencing the src-like tyrosine kinase p60src and phospholipase C." (PMID 31237925, 2019). "Intriguingly, we observed a negative association between E‐cadherin and SSTR5 expression in GH‐producing tumours." (PMID 30843342, 2019). "In 19/21 patients, imaging results could be compared to immunohistological staining for SSTR2a and SSTR5 derived from biopsies of the primary tumor (n=15) or metastases (n=4)." (PMID 26936994, 2016). "Hence, while SSTR2 qualifies as a gene involved in growth arrest in accordance with the proposed anti-tumor function, the reverse may be true for SSTR5." (PMID 39682758, 2024). "In addition, an in vivo octreotide loading test or immunostaining with SSTR2 and SSTR5 in tumor tissues may help to further predict the therapeutic response of SSA." (PMID 35265125, 2022). "However, the [68Ga]Ga-DOTANOC-negative tumor expressed only SSTR5." (PMID 35008325, 2021). "SSTR5 is a predominant inhibitory receptor for glucose-induced insulin secretion and conveys most of the negative impacts of SSAs on glucose metabolism, but how this affects tumor proliferation is unknown." (PMID 35008325, 2021). "Somatostatin receptor 5 may serve as a potential tumor marker for malignancy." (PMID 31336364, 2019). "In addition, a positive correlation has been reported between SSTR5 expression and tumor size." (PMID 31236404, 2019). "However, other somatostatin analogues such as Lanreotide, which have good affinity for SSTR5 in addition to that for SSTR2, may advantageously recognize SSTR5 expressing tumours." (PMID 21143993, 2010). "Namely, various studies based on immunohistochemistry demonstrated the expression of all SSTR1 to SSTR5 on primary NB and, specifically, the overexpression of SSTR2 in the majority of NBs, even in recurrent/refractory tumor disease." (PMID 40064181, 2025).